STAT1 (signal transducer and activator of transcription 1)
Diseases named in the same sentence as STAT1 in open-access papers (continued):
Sharing a sentence is not in itself a finding about the gene and the disease.
atherosclerosis (continued). "This study successfully identified key genes associated with EndMT-related atherosclerosis, such as CD68, TLR2, MYD88, IRF7, STAT1, and IL1B, all of which demonstrate substantial diagnostic potential for detecting atherosclerotic plaques." (PMID 38268851, 2023). "Zhang found that circ_0086296 is upregulated in human carotid artery plaques and can promote ECs injury and atherosclerosis progression via an IFIT1/STAT1 feedback loop by sponging miR-576-3p." (PMID 37990246, 2023). "The in vitro studies were focused on macrophages because of our previous research on ERK1/2 and STAT1 serine 727 phosphorylation on these cells and as they play pivotal roles at all stages of atherosclerosis." (PMID 34569651, 2021). "It is universally acknowledged that inflammatory cytokines are mediators of atherosclerosis, and previous studies have demonstrated that inflammatory genes can be regulated by STAT1–NF-κB or STAT1–IRF through over-expression in their promoters." (PMID 33589571, 2021). "The other interpretation is that the STAT1 dependent but STING independent signaling is also involved in the atherosclerosis protective effect of the compound 3C in vivo." (PMID 33901014, 2021). "Our studies reveal an important role in particular for STAT1 S727 phosphorylation in atherosclerosis development via modulation of plaque inflammation." (PMID 34569651, 2021). "Male mice were used in this study because previous research has shown that deficiency of the cytokine IFN‐γ, which activates ERK1/2 and STAT1, demonstrates gender specific effects on atherosclerosis in ApoE−/− mice." (PMID 34569651, 2021). "NAMPT has also been implicated in mediation of other inflammatory conditions including neuroinflammation, atherosclerosis, and arthritis, and future work will take a closer look at the relevance of Stat1-induced NAMPT in these settings." (PMID 33976173, 2021). "Toll-like receptors can initiate inflammatory responses in atherosclerosis and STAT-1 is involved in the signaling pathways mediated by toll-like receptor 4, resulting in increased expression of several pro-inflammatory and pro-atherogenic mediators." (PMID 33287461, 2020). "The involvement of STAT1 in experimental atherosclerosis has recently been appreciated, especially in immune cells." (PMID 25478796, 2014). "Our study provides evidence to suggest that in ECs and VSMCs STAT1 orchestrates a platform for cross-talk between IFNγ and TLR4, and identifies a STAT1-dependent gene signature that reflects a pro-atherogenic state in human atherosclerosis." (PMID 25478796, 2014). "Another function of STAT1, also possibly contributing to the development or exacerbation of atherosclerosis, occurs in the macrophages." (PMID 24194869, 2013). "Stat1, a signal transducer and activator of transcription, plays a crucial role in the pathology of atherosclerosis resulting from the effects of interferon-γ produced by T cells." (PMID 24063402, 2013). "Recent studies point to a novel function of Stat1 in the pathogenesis of numerous diseases beyond tumorigenesis and host defenses, such as atherosclerosis and other cardiovascular disorders." (PMID 20011528, 2009). "Interestingly, several of these transcription factors, including RUNX3, STAT1, IRF7, and the Th2 hallmark GATA3, had already been implicated in lesion formation in experimental models of atherosclerosis." (PMID 41039608, 2025). "Moreover, STAT1 activation in macrophages has been shown to exacerbate atherosclerosis in animal models, suggesting a critical role for this signaling axis in disease progression." (PMID 40607379, 2025).
atherosclerosis (continued). "With their known inflammation and atherosclerosis-related functions, collectively these STAT1-dependent integrated genes could serve as new biomarkers and therapeutic targets in human atherosclerosis." (PMID 40607379, 2025). "However, the precise mechanisms by which STAT1-mediated IFNγ signaling contributes to atherosclerosis progression remain incompletely understood." (PMID 40607379, 2025). "Likewise, KEGG analysis for the IFNγ-responsive STAT1-dependent integrative genes recognized similar terms, especially connected to lipid and atherosclerosis." (PMID 40607379, 2025). "Downregulation of STAT1 attenuates atherosclerosis and cognitive impairment in T2DM patients." (PMID 38956653, 2024). "circ_0086296, together with miR-576-3p, IFIT1, and STAT1, constitutes a feedback loop that participates in the regulation of atherosclerosis progression, and high circ_0086296 expression was confirmed in the exosomes of serum of patients with atherosclerosis." (PMID 36803975, 2023). "Therefore, the circ_0086296/miR-576-3p/IFIT1/STAT1 feedback loop participates in atherosclerosis progression and contributes to the high circ_0086296 expression observed in the exosomes of serum of patients with atherosclerosis." (PMID 36138395, 2022). "Two previous studies have investigated the role of STAT1 in atherosclerosis." (PMID 34569651, 2021). "Despite such associations, the roles of ERK1/2 and STAT1 S727 phosphorylation in atherosclerosis development in mouse model systems have not been investigated." (PMID 34569651, 2021). "In addition, our studies have shown that an omega‐6 fatty acid, dihomo‐γ‐linolenic acid (DGLA), which attenuates several atherosclerosis‐associated cellular processes in vitro, inhibits IFN‐γ‐induced STAT1 S727 phosphorylation." (PMID 34569651, 2021). "Because the expression of a large number of pro‐atherogenic genes was attenuated by the ERK1−/− and STAT1 S727A genetic modifications, their effects on several macrophage processes associated with atherosclerosis was investigated using BMDM from C57BL/6J, ERK1−/−, and STAT1 S727A mice." (PMID 34569651, 2021). "As exogenous IFN‐γ has been found to enhance atherosclerosis in ApoE−/− mice fed a normal diet, follow‐up studies should investigate the impact of ERK1 deficiency and STAT1 serine S727 phosphorylation on disease development following injection of the cytokine in mice." (PMID 34569651, 2021). "Furthermore, previous studies have reported that Stat1 deficiency instituted by using a bone marrow transplantation technique could not only suppress M1 polarization but also decrease foam cell formation in macrophages and reduce atherosclerosis in ApoE−/− mice." (PMID 31924749, 2020). "Our experimental data provide evidence that TWEAK inhibition ameliorates diabetes-driven atherosclerosis through the attenuation of STAT1 activation and proinflammatory cytokines expression, thus resulting in reduced atherosclerotic lesion development and increased plaque stability." (PMID 28447667, 2017). "IFN-γ plays a role in atherosclerosis via JAK/STAT1 signaling." (PMID 26006249, 2015). "With the proven role of STAT1-dependent signal amplification in endothelial and vascular smooth muscle cells and also atheroma-interacting immune cells, STAT1 target genes represent promising markers of endothelial dysfunction and atherosclerosis development." (PMID 25196434, 2014). "Together, this points to a pro-atherogenic role of STAT1 in vascular cells of atherosclerotic plaques, and suggests the potential of a selection of STAT1-target genes as biomarkers to monitor plaque phenotype in human atherosclerosis." (PMID 25478796, 2014).
atherosclerosis (continued). "Finally, comparative analysis between these scRNAseq data sets and with our in-house HFD ApoE-/- atherosclerosis mouse model bulk RNA-seq data set was used to identify a novel MØ-specific STAT1-dependent integrated gene signature to monitor human atherosclerotic plaque formation." (PMID 40607379, 2025). "Understanding how IFNγ and STAT1 signaling intersect with PU.1 and these epigenetic processes in MØ and MØ subtypes in atherosclerotic plaques could provide new insights into the molecular basis of MØ-specific STAT1-dependent transcription and its potential contribution to atherosclerosis." (PMID 40607379, 2025). "In atherosclerosis, antisense suppression of SOCS3 in APOE -/- mice exacerbated atheroma development, whereas adenovirus-mediated upregulation of SOCS3 in the same model suppressed plaque development, in association with reduction in STAT1 and STAT3-dependent gene expression." (PMID 36172348, 2022). "Moreover, deletion of STAT1 attenuates the progression of atherosclerosis." (PMID 33901014, 2021). "Unfortunately, the roles of ERK1/2 and STAT1 serine 727 phosphorylation in atherosclerosis are poorly understood and were investigated using ERK1 deficient mice (ERK2 knockout mice die in utero) and STAT1 knock‐in mice (serine 727 replaced by alanine; STAT1 S727A)." (PMID 34569651, 2021). "Accordingly, STAT1 inhibitor may be a potential therapeutic strategy for atherosclerosis." (PMID 33287461, 2020). "In addition, STAT1 represents an interesting novel target of therapeutic intervention that has a crucial role in mediating the interplay between damaged vessels and host immunity during the process of atherosclerosis." (PMID 25478796, 2014). "The shortest way in CTPDN mainly divided into three types, AKT1, lipid and atherosclerosis, CAT and chemical carcinogenesis—receptor activation, and AKT1 or HMOX1 with STAT1 together acting on fluid shear stress and atherosclerosis." (PMID 40217538, 2025). "In our study, we identified a subset of 511 differentially expressed genes and 117 STAT1-dependent integrated genes, specific for the VSMC population and connected to VSMC function and atherosclerosis." (PMID 40607379, 2025). "In brief, our data reveal that LSS-induced IKKε phosphorylation activates the downstream transcription factor STAT1 and upregulates NLRP3 expression, ultimately triggering endothelial pyroptosis and atherosclerosis progression." (PMID 38315275, 2024). "STAT1 activation in endothelial cells upregulated the expression of inflammatory factor IL-1β and chemokine CX3CL1, triggering atherosclerosis progression." (PMID 38315275, 2024). "This led to T cell activation and CD40 suppression by STAT1 ODN, presenting a protective effect against atherosclerosis advancement." (PMID 36614305, 2023). "These current studies demonstrate that PTPN2 in macrophages inhibits the development of atherosclerosis by regulating IFN-γ, JAK/STAT1, IL-4/6, and NF-κB-induced inflammation." (PMID 37670950, 2023). "In support of this, an antimalarial drug, artesunate, downregulated IFN induced STAT1 phosphorylation in SLE PBMC's in vitro, which reduced production of macrophage migration inhibitory factor (MIF), a key regulator of both atherosclerosis and SLE." (PMID 33640328, 2021). "Of all STATs especially STAT1, STAT2, and STAT3 have been recognized as prominent modulators of inflammation, especially in immune and vascular cells during atherosclerosis." (PMID 30283459, 2018). "In particular, STAT1, 2 and 3; IRF1 and 8 have recently been recognized as prominent modulators of inflammation, especially in immune and vascular cells during atherosclerosis." (PMID 27166190, 2016). "Therefore, STAT1 could be a promising therapeutic target in atherosclerosis." (PMID 26006249, 2015). "Several mediators that participate in this atherosclerosis‐promoting vascular inflammatory process are regulated by nuclear transport of NFκB and other SRTFs such as AP‐1, NFAT, and STAT1." (PMID 23563994, 2013).
atherosclerosis (continued). "STAT1 is a prominent transcription factor in JAK/STAT signaling pathway, which plays a role in numerous diseases, such as tumor, immune response activation, atherosclerosis, myocardial infarction, heart failure and cardiac hypertrophy." (PMID 38926347, 2024). "Recent studies have suggested that low WSS promotes atherosclerosis by inducing the formation of neutrophil extracellular traps (NETs) through the Piezo1-HDAC2 pathway and triggering endothelial cell pyroptosis via the IKKε/STAT1/NLRP3 pathway." (PMID 39474371, 2024). "STAT1 facilitates epithelial mesenchymal transition (EMT) and acts as a key effector in the interferon signaling pathway, which activates macrophages via STAT1-dependent mechanism in atherosclerosis." (PMID 38268851, 2023). "STAT1 activity is regulated by EP300-dependent acetylation, and that the interaction between EP300 and STAT1 participates in oxidized low-density lipoprotein uptake and foam cell formation, which are responsible for the pathogenesis of atherosclerosis." (PMID 34112215, 2021). "DGLA also attenuates atherosclerosis in ApoE−/− mice although the role of STAT1 S727 phosphorylation has not been investigated." (PMID 34569651, 2021). "To explore the mechanism by which 3C prevents atherosclerosis development, we hypothesized that 3C might suppress JAK2/STAT1 signaling through activating AMPK." (PMID 33901014, 2021). "In addition to STAT3, other STATs, especially STAT1 and STAT2, also play essential roles in atherosclerosis." (PMID 31588227, 2019). "We hypothesize that STAT1-dependent transcriptional changes in vascular cells involved in cross-talk between IFNγ and TLR4, reflect pro-atherogenic responses in human atherosclerosis." (PMID 25478796, 2014). "claimed that m6A modification notably increased the stability of signal transducer and activator of transcription 1 (STAT1) mRNA, which enhanced the promotion of M1 macrophage polarization in blood vessels, leading to an exacerbated local inflammatory response and worsening of atherosclerosis." (PMID 39432244, 2024). "STAT1 has also been identified as an important mediator in the biological response to different Toll like receptors (TLRs), which are innate immune pattern recognition receptors (PRR) expressed on a variety of cells, and initiate and sustain the inflammatory response in atherosclerosis." (PMID 25478796, 2014). "However, the specific role for STAT1 in human atherosclerosis has not been previously reported." (PMID 25478796, 2014).
lung adenocarcinoma (50 papers, 2013 to 2026). A carcinoma that arises from the lung and is characterized by the presence of malignant glandular epithelial cells. "These last processes would be caused in lung adenocarcinoma by the negative regulation of IL-8 transcription in a STAT1-dependent manner relying on SETD2 trimethylation of H3K36." (PMID 39591760, 2025). "Taken together the loss of Stat1 leads to an impaired TNFα mediated immune signaling, resulting in a complete defect to kill tumor cells in our murine model of lung adenocarcinoma." (PMID 30647851, 2018). "As macrophages are able to directly eliminate tumor cells by secreting inflammatory cytokines, we next evaluated the ability of Stat1 deficient M1 macrophages to kill LL/2-luc-M38 lung adenocarcinoma cells used to induce lung tumor in mice." (PMID 30647851, 2018). "Taken together, these results show that Oct4 is associated with Stat1 expression and may be useful as a prognostic marker for lung adenocarcinoma." (PMID 34685622, 2021). "As we could observe that the loss of STAT1 leads to a defect in M1 macrophages in the bone marrow in naïve mice, we next wanted to investigate the consequences of this phenomenon in our murine model of lung adenocarcinoma model." (PMID 30647851, 2018). "As previously discussed, in lung adenocarcinoma a loss of SETD2 favors cell proliferation, migration, invasion and EMT through regulation of the STAT1–IL-8 signaling pathway." (PMID 39591760, 2025). "Studies have found that high STAT1 expression is associated with unfavorable OS rates in patients with PAAD, renal cancer, lung adenocarcinoma, and other malignancies." (PMID 40141028, 2025). "It has been reported that activation of TBK1 and STAT1 played important roles in IFN-γ sensitivity in lung adenocarcinoma." (PMID 38625657, 2024). "This is accompanied by elevated levels of ISG15 and ISGylation that resemble interferon stimulated lung adenocarcinoma cells (A549) and is likely due to constitutive STAT1 activation." (PMID 37756534, 2023). "In another study, the methyltransferase SETD2 was found to inhibit tumor growth and metastasis through STAT1-IL-8 signaling-mediated epithelial-mesenchymal transition in lung adenocarcinoma." (PMID 36726839, 2023). "In patients with lung adenocarcinoma, the expression of Oct4 is related to the expression of STAT1, and Oct4 binds directly to the STAT1 promoter to trans-activate STAT1 in lung adenocarcinoma cells." (PMID 36419898, 2022). "Combined with our research basis, we tried to explore the possible mechanism of primary drug resistance in EFGR mutant lung adenocarcinoma through the interaction between the JAK/STAT1 and JAK/STAT3 pathway." (PMID 36185620, 2022). "As described in the previous section, OSM can inhibit EMP via STAT1, and these effects were concomitant with Slug reduction in lung adenocarcinoma cells." (PMID 34361105, 2021). "In our study, we demonstrated that the stem cell marker Oct4 is overexpressed and, ultimately, results in an anti-apoptosis phenotype through the Stat1/Mcl-1 axis in lung adenocarcinoma." (PMID 34685622, 2021). "Opposite to the pro-EMP role of STAT3, STAT1 activation by OSM has been shown to reduce metastasis of lung adenocarcinoma by STAT1/HDAC1/PIAS4-mediated Slug repression." (PMID 34361105, 2021). "In this study, we show that Stat1 expression is correlated with Oct4 expression in lung adenocarcinoma patients." (PMID 34685622, 2021). "Our results revealed that Oct4 expression is correlated with Stat1 expression in lung adenocarcinoma patients and Oct4 is directly bound to the Stat1 promoter to transactivate Stat1 in lung adenocarcinoma cells." (PMID 34685622, 2021). "Our results support the critical role of the Oct4/Stat1/Mcl-1 axis in cell survival in lung adenocarcinoma." (PMID 34685622, 2021). "Our results suggest that Oct4 acts in apoptosis through the regulation of Stat1 in lung adenocarcinoma." (PMID 34685622, 2021).